ENSG00000212371
Gene: Small nucleolar RNA gene on chromosome 14 (77,466,284 to 77,466,436, forward strand). Ensembl gene ENSG00000212371.
Homologues: Paralogues in human: SNORA46 (67% identical).